PLOD2 (procollagen-lysine,2-oxoglutarate 5-dioxygenase 2)
Diseases named in the same sentence as PLOD2 in open-access papers (continued):
Sharing a sentence is not in itself a finding about the gene and the disease.
breast carcinoma (continued). "In summary, our findings revealed a new stromal collagen network that favors tumor invasion and metastasis establish between breast cancer cells and surrounding adipocytes at the tumor invasive front, and identified PLOD2 as a therapeutic target for metastatic breast cancer treatment." (PMID 31170987, 2019). "PLOD1 and PLOD2 expression was induced by hypoxia in breast cancer cells." (PMID 31231467, 2019). "In 1996, PLOD2 was first reported in breast cancer research by Smith." (PMID 31455288, 2019). "Inhibition of PLOD2 may be sufficient to suppress migration and invasion in vitro and to alleviate lung and liver metastasis of breast cancer cells in vivo." (PMID 30563531, 2018). "To further verify that adipokines contribute to adipocyte-mediated effects, we investigated the expression of PLOD2 in breast cancer cells cultured in conditioned medium (CM) obtained from preadipocytes, adipocytes, or adipocytes previously grown in the presence of cancer cells." (PMID 30563531, 2018). "Interestingly, 3 h to 72 h of adipocyte coculture increased PLOD2 expression in breast cancer cells, with the most significant upregulation occurring between 48 h and 72 h." (PMID 30563531, 2018). "However, in our study we confirmed that IL-6 and leptin were responsible for the adipocyte-mediated upregulation of PLOD2 in breast cancer." (PMID 30563531, 2018). "In addition, hypoxia-inducible factor 1 (HIF-1) also activates transcription of PLOD1 in breast cancer cells; however, function PLOD2 is more important for HIF-1-induced cancer progression." (PMID 30003082, 2018). "Thus, our research reveals a novel interaction between adipocytes and breast cancer and lays the way for clinical study aimed at exploring the interaction between adipocytes and PLOD2 in obese breast cancer patients." (PMID 30563531, 2018). "And PLOD2 is positively correlated with the stage of breast cancer." (PMID 30563531, 2018). "Therefore, we postulated that coculture of adipocytes with breast cancer cells promoted PLOD2 expression via activation of the JAK/STAT, MEK/ERK and PI3K/AKT signaling pathways." (PMID 30563531, 2018). "Further, depletion of PLOD2 attenuates adipocyte-induced breast cancer cell migration in vitro." (PMID 30563531, 2018). "Moreover, knockdown of PLOD2 inhibits breast cancer cell migration and metastasis both in vitro and in vivo." (PMID 30563531, 2018). "Taken together, these results suggest that PLOD2 upregulation may stimulate the enhanced migration of breast cancer cells following coculture with adipocytes." (PMID 30563531, 2018). "Taken together, these results suggest that PLOD2 promotes breast cancer metastasis in vivo." (PMID 30563531, 2018). "Therefore, our results clearly suggest that adipocyte-derived IL-6 and leptin promote the invasive phenotype of breast cancer cells via upregulation of PLOD2 both in vitro and in vivo." (PMID 30563531, 2018). "Taken together, these findings reveal that high PLOD2 expression may serve as a clinical biomarker for poor prognosis in breast cancer patients." (PMID 30563531, 2018). "Furthermore, we examined the correlations between relapse-free survival (RFS) of different stages status breast cancer and PLOD2 expression were analyzed by Kaplan-Meier plotter." (PMID 30563531, 2018). "Furthermore, increased PLOD2 expression in breast tumors correlated with poor prognosis of breast cancer patients." (PMID 30563531, 2018). "We next examined PLOD2 expression cross a panel of breast cancer cell lines." (PMID 30563531, 2018). "Mechanistically, adipocyte-derived interleukin-6 (IL-6) and leptin may facilitate PLOD2 upregulation in breast cancer cells and promote breast cancer metastasis in tail vein metastasis assays." (PMID 30563531, 2018).
breast carcinoma (continued). "Treatment with a murine IL-6 blocking antibody or depletion of OBR abrogated both the expression of PLOD2 and adipocyte-stimulated metastasis, indicating that PLOD2 plays an important role in mediating breast cancer metastasis via adipocyte-derived IL-6 and leptin." (PMID 30563531, 2018). "Further, high PLOD2 expression correlated with poor prognosis of breast cancer patients." (PMID 30563531, 2018). "Thus, we next examined PLOD2 expression at different time points in breast cancer cells cocultured with adipocytes." (PMID 30563531, 2018). "We found that PLOD2 was upregulated in breast cancer tissues compared with para-cancerous tissues." (PMID 30563531, 2018). "Based on the observation that adipocyte-derived IL-6 and leptin promoted PLOD2 expression in breast cancer cells, we next explored whether IL-6 and leptin activated JAK/STAT and AKT signals in vitro." (PMID 30563531, 2018). "Furthermore, breast cancer cells cocultured with adipocytes or treated with either IL-6 or leptin displayed increased PLOD2 expression and activated JAK/STAT3 and AKT signaling pathways." (PMID 30563531, 2018). "Furthermore, Gilkes and colleagues recently demonstrated that the metastatic marker PLOD2 is a hypoxia-inducible gene and is required for breast cancer metastasis to lymph and lung." (PMID 24919196, 2014). "Additionally, PLOD2 knockdown substantially reduced metastasis of breast cancer cells in mice." (PMID 36140753, 2022). "In addition, the driving force of adipocytes in breast cancer metastasis can also be attributed to cytokine-mediated communication between these cells, which results in the upregulation of metastasis-related factors such as PLOD2 and MMP-2 in cancer cells." (PMID 33371368, 2020). "Therefore, our study reveals a potential new novel network of tumor invasion and metastasis that is established between breast cancer cells and surrounding adipocytes, while targeting PLOD2 may be a credible therapeutic strategy for breast cancer metastasis." (PMID 31170987, 2019). "Therefore, PLOD2 may be a potential therapeutic target of breast cancer, since impeding PLOD2 is able to directly inhibit cancer cell migration and indirectly block the role of stromal cell-derived collagen reorganization." (PMID 31170987, 2019). "Furthermore, our results may indicate that obese breast cancer patients more likely to show high expression of PLOD2 which predict a poor prognosis." (PMID 30563531, 2018). "Therefore, in this study we investigated whether adipocyte-derived adipokines could promote breast cancer metastasis by regulating PLOD2 expression." (PMID 30563531, 2018). "Furthermore, excessive accumulation of fat may contribute to the higher expression of PLOD2 and correlation with breast cancer patient poor prognosis." (PMID 30563531, 2018). "Combining this observation with our results showing that IL-6 enhances PLOD2 expression in the short term, we hypothesized that adipocyte coculture would increase PLOD2 expression in the short term and maintain this expression in the long term in breast cancer cells." (PMID 30563531, 2018). "Therefore, our results suggest that PLOD2 plays a vital role in adipocyte-dependent invasive activity and high PLOD2 expression may predict poor survival in breast cancer patients." (PMID 30563531, 2018). "Therefore, in order to solve these problems, we can use the transgenic mouse model of breast cancer to compensate the difference of microenvironment in the xenograft model in our subsequent research, which can verify the role of PLOD2 in breast cancer metastasis." (PMID 30563531, 2018). "Therefore, we speculated that maybe the high expression of PLOD2 in lung and liver normal tissues induced the formation of pre-metastatic lesions, which was conductive to the metastasis of breast cancer." (PMID 30563531, 2018). "Up-regulation of P4HA2 and PLOD2 by RASSF1C was also confirmed in lung and breast cancer cells in vivo using mouse models." (PMID 36826019, 2023).
breast carcinoma (continued). "It was demonstrated that DTCs derived from breast cancer cell secrete collagen crosslinking enzyme LOX and PLOD2, thereby amplifying focal adhesion signaling mediated by integrin by stiffening ECM45,46." (PMID 31882647, 2019). "PLOD2 expression in invasive front of adipose tissues and PAI-1 expression in breast cancer tissues were both found to be higher compared with that of the clinical samples of normal adipose tissue or normal mammary tissue." (PMID 31170987, 2019). "We next examined the expression of PLOD2 following treatment of MDA-MB-231 and MDA-MB-468 breast cancer cells with leptin." (PMID 30563531, 2018). "Inhibition of STAT3 activity using a pharmacological inhibitor of JAK (ruxolitinib) decreased PLOD2 expression in adipocyte cocultured MDA-MB-231 and MDA-MB-468 breast cancer cells." (PMID 30563531, 2018). "And further coexpression analysis indicated that GP130 and PLOD2 or OBR and PLOD2 were simultaneously expressed in breast cancer tissue microarray." (PMID 30563531, 2018). "A 3-day exposure to leptin significantly increased PLOD2 expression and activated phosphorylation of STAT3 and AKT in MDA-MB-231 and MDA-MB-468 breast cancer cells." (PMID 30563531, 2018). "Our study reveals that adipocyte-derived IL-6 and leptin promote PLOD2 expression by activating the JAK/STAT3 and PI3K/AKT signaling pathways, thus promoting breast cancer metastasis." (PMID 30563531, 2018). "For instance, silencing PLOD2 expression in the breast cancer cell line MDA-MB 231 reduces cancer metastasis and collagen deposition in the primary tumor tissue; interestingly, PLOD2 expression has little effect on the primary tumor growth." (PMID 30003082, 2018). "Here, we demonstrated that protein levels of GP130 and PLOD2 were significantly increased in MDA-MB-231 and MDA-MB-468 breast cancer cells cocultured with adipocytes." (PMID 30563531, 2018). "PLOD2 protein expression was also increased in MDA-MB-231 and MDA-MB-468 breast cancer cells cocultured with adipocytes." (PMID 30563531, 2018). "PLOD2 protein and SDFR1 mRNA were detected in breast carcinoma cells and in a small but consistent fraction of peritumor stroma cells (78 out of 100, 78% positive, and 55 out of 79, 70% positive, respectively)." (PMID 14737219, 2004). "While PLOD2 depletion did not inhibit collagen deposition in breast cancer in vitro or in vivo, as in the case of P4HAs, it did decrease tumor stiffness." (PMID 36140753, 2022). "In sum, hypoxia directly regulates ECM composition via multiple enzymes and, as such, P4HA1, P4HA2, PLOD2, and LOX enzymes could be used as biomarkers in breast cancer progression." (PMID 36140753, 2022). "In addition to promoting cancer cell metastasis through EMT, leptin can also promote the expression of lysine hydroxylase-2 (PLOD2) by activating the PI3K/AKT signaling pathway, thus promoting the metastasis of breast cancer." (PMID 34485124, 2021). "Moreover, it has been reported that in breast cancer, HIF-1 activates PLOD1 and PLOD2 transcription under hypoxic conditions, regulates collagen cross-linking, and promotes lymph node and lung metastasis." (PMID 33420370, 2021). "Interestingly, our present study indicated breast cancer cells secreted PAI-1 led to the activation of PLOD2 expression in adipocytes microenvironment, while the addition of tiplaxtinin further abrogated PLOD2 activation in CAAs." (PMID 31170987, 2019). "PLOD2 is induced by hypoxia-inducible factor-1α (HIF-1α) under hypoxia condition, which in turn enhance hypoxia-induced Epithelial-Mesenchymal Transition (EMT) phenotypes in glioma cells and breast cancer cells." (PMID 30003082, 2018). "We next explored whether the expression of IL-6 and leptin receptors, which might mediate PLOD2 expression, was increased in MDA-MB-231 and MDA-MB-468 breast cancer cells after coculture with adipocytes." (PMID 30563531, 2018).
breast carcinoma (continued). "To further confirm whether IL-6 and leptin could induce PLOD2 expression, we treated MDA-MB-231 and MDA-MB-468 breast cancer cells with recombinant human IL-6 protein." (PMID 30563531, 2018). "Additionally, treatment with a phosphatidylinositol 3-kinase inhibitor (LY294002) decreased PLOD2 expression in MDA-MB-231 and MDA-MB-468 breast cancer cells." (PMID 30563531, 2018). "The results showed that the expression of PLOD2 was positively correlated with the stage of breast cancer, and in particular in breast cancer patients at stage III but not at stage I and II." (PMID 30563531, 2018). "Hence, our study suggested PAI-1 may be a valuable target in breast cancer, targeting PAI-1 could inhibit cancer cells migration and abrogated PLOD2-mediated collagen reorganization in tumor microenvironment." (PMID 31170987, 2019). "a PLOD2 mRNA levels in breast cancer tissues were assessed in 625 non-TNBC and 79 TNBC tissues." (PMID 30563531, 2018).
Bruck syndrome (21 papers, 2011 to 2025). Bruck syndrome is characterized by the association of osteogenesis imperfecta and congenital joint contractures. "Three patients were identified with mutations in the P3H1, LEPRE, CRTAP, SERPINF1, PLOD2 (Bruck syndrome), TGFB1, and SGMS2 genes (Calvarial Doughnut Lesions with Bone Fragility)." (PMID 39941180, 2025). "In Bruck syndrome, mutations in Plod2 were shown to be causative of collagen I underhydroxylation, leading to osteoporosis, scoliosis, and joint contractures." (PMID 39769264, 2024). "Mutations in the PLOD2 gene cause the Bruck syndrome, which is characterized by the unusual combination of skeletal changes resembling osteogenesis imperfecta with congenital contractures of the large joints." (PMID 33923324, 2021). "Mutations in PLOD2 cause Bruck syndrome (BS), a rare congenital connective tissue disorder characterized by a combination of joint contractures with various skeletal anomalies." (PMID 31935848, 2020). "Bruck Syndrome is a connective tissue disease associated with inactivating mutations in lysyl hydroxylase 2 (LH2/PLOD2) or FK506 binding protein 65 (FKBP65/FKBP10)." (PMID 28378777, 2017). "Mutations in PLOD2 have been associated with the clinical condition Bruck syndrome 2 [OMIM:609220], which is characterized by abnormal collagen cross-linking in bone, osteopenia and multiple fractures in mice." (PMID 22394585, 2012). "PLOD2 mutations in humans cause Bruck syndrome, a disease marked by bone fragility and congenital joint contractures, which is faithfully modeled by Plod2-deficient zebrafish that exhibit a shortened body axis and severe skeletal abnormalities with evidence of bone fragility." (PMID 40028343, 2025). "Bruck syndrome 2 is caused by homozygous mutation in the PLOD2 gene on chromosome 3q24." (PMID 36258204, 2022). "Mutations in PLOD2 are associated with Bruck syndrome, a recessive condition resembling OI." (PMID 28884682, 2017). "Patients with contractures will be scanned for presence of variants in the PLOD2 and FKBP10 genes to specify presence of a Bruck syndrome diagnosis." (PMID 31447884, 2019). "Thus far, PLOD2-related studies have been performed on fibrotic diseases and cancers such as Bruck syndrome, Ehlers–Danlos syndrome and carcinomas." (PMID 38760576, 2024). "Meanwhile, PLOD2 induced the differentiation of bone marrow stromal cells, and the abnormal expression of PLOD2 could result in Bruck syndrome, which is manifested as osteogenesis imperfection, bone fragility, and brittle fracture." (PMID 35479581, 2022). "Bruck Syndrome (BRKS) is a rare type of recessive osteogenesis imperfecta (OI) and consists of two subtypes, BRKS1 and BRKS2, which are caused by variations in FKBP10 and PLOD2 genes, respectively." (PMID 33664768, 2021). "Diagnosis of Bruck syndrome depended on clinical and laboratory findings, including urine lysyl oxidation assays, negative screens for mutations in the PLOD2 gene, and the finding of congenital contractures in the presence of bone fragility." (PMID 20839288, 2011).
glioma (21 papers, 2017 to 2024). A benign or malignant brain and spinal cord tumor that arises from glial cells (astrocytes, oligodendrocytes, ependymal cells). "The same study also showed that increasing PLOD2 protein levels were associated with increasing tumor grade in glioma." (PMID 35682709, 2022). "Analysis of The Cancer Research Atlas (TCGA) and the REMBRANDT databases indicated that PLOD2 can constitute an effective diagnostic marker to distinguish lower grade gliomas from GBM." (PMID 29165393, 2017). "In this study, we characterized the biological roles of PLOD2 in glioma tumorigenesis and investigated the underlying mechanisms." (PMID 28410212, 2017). "Such functions of PLOD2 might underlie its ability to stimulate glioma cells to infiltrate the brain parenchyma." (PMID 28423580, 2017). "The area under the receiver operating characteristic (ROC) curve was 0.785 (CI, 0.785–0.828), indicating that PLOD2 might be effective as a diagnostic marker to distinguish glioblastoma from lower grade gliomas." (PMID 28423580, 2017). "Moreover, higher level of PLOD2 was associated with shorter overall survival in patients with glioma, indicating that PLOD2 may serve as a prognostic indicator for glioma." (PMID 28410212, 2017). "PLOD2 modulates the immune microenvironment and tumor progression of glioma, in which CD44 was the critical downstream molecule." (PMID 36776876, 2023). "PLOD2 is upregulated in glioma samples and increases invasion, migration and proliferation of glioma cells by modulating the phosphoinositide 3‐kinase/Akt pathway." (PMID 34739189, 2022). "Hypoxia-induced PLOD2 promotes glioma cell migration and invasion via modulation of the PI3K/AKT signaling pathway and promotion of EMT." (PMID 35614390, 2022). "In the study of glioma, PLOD2 is induced by hypoxia-inducible factor-1α (HIF-1α) and then activates the PI3K/AKT signaling pathway, which eventually leads to the occurrence of EMT." (PMID 35912206, 2022). "In glioma, the expression of PLOD2 is increased under hypoxia, which can promote tumor proliferation and metastasis through PI3K/AKT signaling." (PMID 35280516, 2022). "Knockdown of PLOD2 in glioma inactivates PI3K/Akt signaling, resulting in inhibition of invasion and metastatic formation." (PMID 33807594, 2021). "In the central nervous system, some researchers have reported that hypoxia-induced PLOD2 can promote tumorigenesis via PI3K/Akt signaling in glioma." (PMID 33503035, 2021). "PLOD2 knockdown inhibited glioma cell proliferation, migration and invasion by inactivating PI3K/Akt signaling." (PMID 33807594, 2021). "PLOD3 and PLOD2 are overexpressed and secreted by cells of lung cancer, glioma, glioblastoma, and pancreatic duct adenocarcinoma." (PMID 33807594, 2021). "Both PLOD2 and PLOD3 had been reported to be highly expressed in gliomas and were associated with tumor progression and prognosis." (PMID 34040895, 2021). "Previous glioma studies that manipulated collagen-modifying enzymes, including PLOD2 and LOX knockdown, demonstrated similar results." (PMID 29644003, 2018). "Taken together, these data demonstrate that hypoxia-induced PLOD2 promotes EMT via PI3K/Akt signaling in glioma." (PMID 28410212, 2017). "Knockdown of PLOD2 inhibited proliferation, migration and invasion of glioma cells in vitro and in vivo." (PMID 28410212, 2017). "Here, we mined glioma microarray datasets to examine the expression profile of PLOD2 in the development of human glioma." (PMID 28423580, 2017). "PLOD2 mRNA expression was found to be significantly increased (~ 3-fold; P < 0.0001) in glioblastoma samples compared to normal brain and lower grade gliomas." (PMID 28423580, 2017). "Knockdown of PLOD2 modulated multiple EMT-associated proteins and thus blocked glioma cell migration and invasion both in vitro and in vivo." (PMID 28410212, 2017).